SPMIP11 (sperm microtubule inner protein 11)
Description:
Microtubule inner protein (MIP) part of the dynein-decorated doublet microtubules (DMTs) in flagellum axoneme. May serve to reinforce and thus stabilize the microtubule structure in the sperm flagella.
Synonyms: TEX49; LINC00935
Gene: Protein-coding gene on chromosome 12 (48,727,435 to 48,765,790, forward strand). Ensembl gene ENSG00000257987.
Subcellular location: Cytoplasm, cytoskeleton, flagellum axoneme
Gene Ontology:
Biological process: flagellated sperm motility
Cellular component: axonemal A tubule inner sheath; sperm flagellum
Homologues: Orthologues: chimpanzee SPMIP11 (99% identical), macaque SPMIP11 (95% identical), dog SPMIP11 (89% identical), pig SPMIP11 (87% identical), rabbit SPMIP11 (85% identical), guinea pig SPMIP11 (84% identical), mouse Spmip11 (80% identical), rat Spmip11 (74% identical).